ANGPTL3 (angiopoietin like 3)
Diseases named in the same sentence as ANGPTL3 in open-access papers (continued):
Sharing a sentence is not in itself a finding about the gene and the disease.
dyslipidemia (continued). "ANGPTL3 could be involved in the development of dyslipidemia, in addition to proteinuria, during PNS pathogenesis." (PMID 35399079, 2022). "An increasing number of epidemiologic, genetic, and genome‐wide association studies suggest that reducing plasma ANGPTL3 levels by inhibiting hepatic ANGPTL3 synthesis will benefit apolipoprotein B levels and improve the metabolic measurements related to dyslipidemia and atherosclerosis." (PMID 35712827, 2022). "Therefore, research on the treatment of dyslipidemia and atherosclerosis with angiopoietin-like 3 and Angptl4-related antibodies has also emerged, although such treatment has not yet been widely used in clinical practice." (PMID 36285165, 2022). "The rational design of oral, small molecules as ANGPTL3 inhibitors may serve as a novel pharmacological approach for the treatment of dyslipidemia." (PMID 34298929, 2021). "The development of ANGPTL3 inhibitors from natural antioxidant flavonoids may lead to effective strategies against dyslipidemia." (PMID 34576019, 2021). "In aggregate, these data indicate that ANGPTL3 inhibition could be considered an alternative therapeutic target for dyslipidemia, dysglycemia, and possible reduction of atherosclerotic lesion size." (PMID 30944669, 2019). "Future trials will reveal if ANGPTL3 inhibition could be considered an alternative therapeutic target for dyslipidemia and dysglycemia." (PMID 30944669, 2019). "Treatment with the fully human monoclonal ANGPTL3-blocking antibody evinacumab of individuals with mixed dyslipidemia with borderline high triglycerides prompted substantial, sustained reductions in triglycerides and VLDL-C levels in 2 randomized, double-blind, placebo-controlled, Phase 1 studies." (PMID 31242752, 2019). "These investigations have suggested that ANGPTL3 may be a novel therapeutic target in the management of dyslipidemias in humans." (PMID 29752428, 2019). "Results have demonstrated that inactivation of Angptl3 in mice could obviously reduce the level of TG, LDL-C and the atherosclerotic lesion size, leading to a lower risk for dyslipidemia and CVD." (PMID 29334984, 2018). "Therefore, we can use the relevant technology to inactivate ANGPTL3 to treat dyslipidemia, obesity and CVD." (PMID 29334984, 2018). "They demonstrate that hepatic miR-27b is responsive to lipid levels and regulates the expression of two key metabolic genes, angiopoietin-like 3 (ANGPTL3) and glycerol-3-phosphate acyltransferase 1 (GPAM), which have been previously implicated in the pathobiology of dyslipidemia." (PMID 29286302, 2017). "Furthermore, anti‐dyslipidemia vaccine therapies targeting ANGPTL3 will be a hot research topic." (PMID 38344397, 2024). "ANGPTL3, identified as a promising lipid-lowering therapy for atherosclerotic cardiovascular disease through the regulation of lipoprotein metabolism and lipid levels, may also serve as a potential therapeutic target for kidney injury mediated by dyslipidemia." (PMID 38584832, 2024). "Due to the increasing rate of diabetes and the importance of ANGPTL3 and ANGPTL4 in the pathogenesis of diabetes through possible association with metabolic syndrome, it seems there is a relationship between these glycoproteins with metabolic syndrome especially in patients with diabetes." (PMID 38140923, 2023). "Thus, ANGPTL3 is considered a promising pharmacological target for treatment of dyslipidemia." (PMID 34298929, 2021). "Emerging studies have focused on ANGPTL3 inhibition via antisense oligonucleotides (ASOs) and monoclonal antibody-based therapies, which have been carried out in mouse or monkey models and in human clinical studies for the management of dyslipidemia and ASCVDs." (PMID 34298929, 2021). "In this article, we review the current understanding of ANGPTL3, focusing on its role in the modulation of lipoprotein metabolism, dyslipidemia, and cardiovascular events, and discuss its application as a therapeutic target for the treatment of dyslipidemia and ASCVDs." (PMID 34298929, 2021).
dyslipidemia (continued). "Finally, we introduce two update reports on the antisense oligonucleotide and monoclonal antibody-based inactivation of ANGPTL3 in human clinical trials, to identify that ANGPTL3 could be a novel and effective target for the treatment of dyslipidemia and CVD." (PMID 29334984, 2018). "Angiopoietin-like 3 proteins have emerged as a new class of lipid metabolism modulators which may serve as a potential novel therapeutic target for reducing plasma lipoprotein and treatment of metabolic syndrome." (PMID 28971105, 2017). "ANGPTL3 has been shown to reduce TG and LDL-c levels, and has therefore emerged as a novel therapeutic target for dyslipidemia." (PMID 38462608, 2024). "The ARCHES-2 (Study of ARO-ANG3 in Adults with Mixed Dyslipidemia) phase II b study demonstrated that ARO-ANG3 significantly decreased ANGPTL3 expression and atherogenic triglyceride-rich lipoproteins, LDL-C and total apoB, in patients with mixed dyslipidemia." (PMID 38592091, 2024). "Therapeutic strategies that downregulate ANGPTL3, thereby reducing TGs and LDL-c in patients with dyslipidemia, have attracted increasing attention." (PMID 38462608, 2024). "Both ANGPTL3 and ANGPTL4 have been utilized as novel therapeutic targets for the treatment of dyslipidemia." (PMID 38160757, 2023). "Contemporary RNA-based antisense oligonucleotides and small interfering RNA’s for apoC3 and the angiopoietin-like 3 (ANGPTL3) profoundly attenuate plasma triglyceride in familial chylomicronemia, severe hypertriglyceridemia, dyslipidemia and T2DM." (PMID 36875491, 2023). "ANGPTL3 has been reported to play a critical role in the inhibition of LPL activity to regulate atherogenic TGRL metabolism in plasma and dyslipidemia." (PMID 36293338, 2022). "These clinical studies indicated that inactivation of ANGPTL3 by inhibitors effectively ameliorates plasma TGs, LDL-C and lipoproteins in dyslipidemia, and thus, ANGPTL3 inhibition shows potential benefits in patients with ASCVDs." (PMID 36293338, 2022). "Similar to ANGPTL3 ASO, ANGPTL3 RNAi significantly reduced plasma triglycerides, HDL-C, and LDL-C levels in different mouse models of dyslipidemia." (PMID 34581310, 2021). "ANGPTL3 has been reported to be mainly involved in the suppression of LPL activity to affect atherogenic TGRL metabolism and dyslipidemia." (PMID 34576019, 2021). "Recently, targeting ANGPTL3 and ANGPTL8 to lower circulating TGs levels in the treatment of dyslipidemia is also pursued." (PMID 34356847, 2021). "Additional novel findings in our study are the inverse correlations of ANGPTL3/8 and ANGPTL4/8 with HDL, and the direct correlations of both complexes with all other metabolic syndrome markers." (PMID 32487544, 2020). "In human serum, ANGPTL3/8 and ANGPTL4/8 complexes both increased postprandially, correlated negatively with HDL, and correlated positively with all other metabolic syndrome markers." (PMID 32487544, 2020). "The angiopoietin-like protein 3/8 complex (ANGPTL3/8) inhibits lipoprotein lipase (LPL) activity, primarily in oxidative tissues, and does so more potently than ANGPTL3, making ANPTL3/8 an attractive target for treating dyslipidemia." (PMID 40640392, 2025). "This study was aimed to investigate the protein levels of ANGPTL3 and 4 in the serum of type 2 diabetic patients with metabolic syndrome in comparison to the type 2 diabetic patients without metabolic syndrome and the control group." (PMID 38140923, 2023). "In addition, we also listed several novel identified modulatory biomarkers which play an important role in the regulation of dyslipidemia induced by hypothyroidism, including PCSK9, ANGPTL3, ANGPTL8, FGF-21, FGF-19, and several microRNAs." (PMID 34784265, 2022). "Our findings support the hypothesis that tangeretin exerts a lipid-lowering effect by modulating the LXRα-ANGPTL3-LPL pathway, and thus, it can be used as a potential phytochemical for the prevention or treatment of dyslipidemia." (PMID 34576019, 2021).
dyslipidemia (continued). "ANGPTL3 was found to be significantly elevated in obese children with metabolic syndrome (MetS) in comparison with those without MetS." (PMID 34422408, 2021). "Recent studies revealed an association between ANGPTL3 and ANGPTL8 with lipid biomarkers in adults, young obese non-diabetic men, children, and adolescents with obesity and metabolic syndrome." (PMID 34959891, 2021). "For ANGPTL3/8, the positive correlation with TG and other markers of metabolic syndrome was not surprising." (PMID 32487544, 2020). "Here, however, we did not observe a positive correlation between circulating ANGPTL3 levels and dyslipidemia." (PMID 29538435, 2018). "Recent studies have demonstrated that ANGPTL3 suppression by antibody or antisense oligonucleotides represents a new therapeutic strategy to reduce plasma LDL cholesterol and TG levels for patients with dyslipidemia." (PMID 29538435, 2018). "In a cross-sectional study including 1770 Caucasian subjects, plasma ANGPTL3 and ANGPTL4 concentrations showed different relationships with plasma lipids; ANGPTL3 was positively associated with LDL cholesterol and HDL cholesterol and not with metabolic syndrome traits including TGs." (PMID 26739706, 2016). "For example, Vupanorsen, an ASO drug that inhibits the synthesis of Angiopoietin-like 3 (ANGPTL3) protein, demonstrated a notable reduction in non-HDL cholesterol levels in patients with dyslipidemia under statin treatment." (PMID 38706718, 2024).
familial hypercholesterolemia (56 papers, 2018 to 2026). An inheritable form of hyperlipidemia, in which there are excess lipids in the blood. "Individuals with ANGPTL3 deficiency exhibit combined hypolipidemia, and an ANGPTL3 inhibitory antibody has been approved for treating homozygous familial hypercholesterolemia." (PMID 39171527, 2024). "Targeting lipid-modulating genes such as angiopoietin-related protein 3 (ANGPTL3) with gene editing offers hope for a permanent solution to lower cardiovascular disease risks associated with hypercholesterolemia." (PMID 37322547, 2023). "Prior studies have shown that plasma ANGPTL3 levels were 15% lower in statin-treated familial hypercholesterolemia patients compared with statin-naive patients." (PMID 40924496, 2025). "Evinacumab, a monoclonal antibody described as an anti-ANGPTL3 antibody approved for treatment of homozygous familial hypercholesterolemia, was recently shown to be a more potent inhibitor of ANGPTL3/8 than of ANGPTL329." (PMID 40640392, 2025). "With regard to adjunctive therapies, the use of lomitapide (an MTP inhibitor) or evinacumab (an ANGPTL3 inhibitor) was considered for eligible patients with refractory hypercholesterolemia." (PMID 41404428, 2025). "Evinacumab is a monoclonal antibody that targets and inhibits ANGPTL3 to treat familial hypercholesterolemia." (PMID 40264627, 2025). "Treatment with evinacumab, an antibody against ANGPTL3, has already been approved as treatment for pediatric patients with homozygous familial hypercholesterolemia, with successful results." (PMID 40503438, 2025). "Evinacumab is a monoclonal antibody (mab) that inhibits ANGPTL3 and is approved for treating homozygous hypercholesterolemia." (PMID 38414008, 2024). "A monoclonal antibody, Evinacumab, inhibiting ANGPTL3, is approved for use in the United States in patients with homozygous familial hypercholesterolemia." (PMID 38455763, 2024). "Monoclonal antibodies have further been applied in the management of hypercholesterolemia via inhibition of ANGPTL3." (PMID 36839781, 2023). "In a phase IIb trial, administration of vupanorsen, an ASO targeting hepatic ANGPTL3, to patients with hypercholesterolemia and hypertriglyceridemia significantly reduced triglycerides together with a modest decrease in LDL-cholesterol." (PMID 37200978, 2023). "GalNAc-LNPs were formulated with an adenine base editor 8.8-m (ABE8.8) mRNA and a guide RNA (gRNA) targeting the mouse Angptl3 or Pcsk9 genes—well-validated therapeutic targets for the treatment of hypercholesterolemia." (PMID 37188660, 2023). "The condition known as non-alcoholic fatty liver disease (NAFLD) is correlated with hypercholesterolemia and abnormal expression of a lipometabolic regulator, known as angiopoietin-like protein 3 (ANGPTL3)." (PMID 37375810, 2023). "A monoclonal antibody (evinacumab) approach directed against ANGPTL3 effectively reduced LDL-C in patients with homozygous familial hypercholesterolemia and refractory hypercholesterolemia." (PMID 36580204, 2023). "These attributes made ANGPTL3 a very attractive new target for the treatments of hypercholesterolemia and sHTG." (PMID 37642858, 2023). "Preclinical studies have established the prospects for the treatment of homozygous familial hypercholesterolemia by targeting the ANGPTL3 gene in the liver." (PMID 34981785, 2022). "Inhibition of ANGPTL3 showed the greatest effect and was even beneficial in patients with familial hypercholesterolemia." (PMID 36138787, 2022). "This condition prompted the development of ANGPTL3 inhibitors to treat an almost opposite phenotype: homozygous familial hypercholesterolemia." (PMID 36203122, 2022). "An ANGPTL3 inhibitor, evinacumab is administered by once monthly infusion to treat homozygous familial hypercholesterolemia." (PMID 34922811, 2022).
familial hypercholesterolemia (continued). "The previously-mentioned angiopoietin-like protein-3 (ANGPTL3) inhibitors (evinacumab) recently introduced in familial hypercholesterolemia follow the same development route as PCSK9 modulators." (PMID 34199468, 2021). "In a phase II trial of ANGPTL3 inhibition involving 9 patients with homozygous familial hypercholesterolemia, evinacumab treatment resulted in a mean reduction from baseline of 49% in the LDL-C level." (PMID 34298929, 2021). "Evinacumab is an anti-ANGPTL3 monoclonal antibody, which has been used in the treatment of familial hypercholesterolemia." (PMID 34744709, 2021). "Evinacumab is a fully human monoclonal antibody directed toward ANGPTL3 that can reduce the TG level in healthy people and patients with homozygous familial hypercholesterolemia." (PMID 32440963, 2020). "The human monoclonal antibody against ANGPTL3, named evinacumab, has been approved by the Food and Drug Administration as a new drug for treating familial hypercholesterolemia." (PMID 29940978, 2018). "In addition, Verve is developing VERVE-201, which targets ANGPTL3, offering an alternative therapeutic strategy focused on remnant cholesterol metabolism in patients with refractory hypercholesterolemia." (PMID 40465697, 2025). "Given the availability of a monoclonal antibody against ANGPTL3 already used in patients with familial hypercholesterolemia, these results warrant further investigation of whether ANGPTL3 inhibition has therapeutic potential in ovarian cancers." (PMID 38414008, 2024). "The totality of evidence suggests that ANGPTL3 inhibition seems to be a better target for the treatment of hypercholesterolemia than sHTG, while apo-CIII seems to be much more promising for the treatment of sHTG and has at best no or negative effects on LDL-C levels." (PMID 37642858, 2023). "Moreover, ANGPTL3 is already being utilized as a target; the Food and Drug Administration (FDA) has recently approved Evinacumab, a monoclonal antibody against ANGPTL3, as a lipid-lowering agent for individuals with familial hypercholesterolemia." (PMID 38189043, 2023). "Evinacumab, a human monoclonal antibody against angiopoietin-like protein 3 (ANGPTL3), has recently been approved by the U.S. Food and Drug Administration as an add-on therapy for homozygous familial hypercholesterolemia (HoFH) in patients of 12 years and older." (PMID 37630982, 2023). "Results of ARO-ANG3 in hypercholesterolemia patients on a stable lipid-lowing regimen showed ANGPTL3 levels dropped by 79–88% on average, and mean maximum reductions in LDL-C was up to 42% (Arrowhead Reports Interim Clinical Data on Cardiometabolic Candidates Aro-Apoc3 and Aro-Ang3, 2020)." (PMID 35754818, 2022). "Preliminary results for a phase 1 study in healthy adult volunteers or patients with dyslipidemia, including familial hypercholesterolemia and severe hypertriglyceridemia, indicate potent and prolonged inhibition of ANGPTL3 levels (up to 93%) after two doses of ARO-ANG3." (PMID 35459248, 2022). "Only medications that inhibit cholesteryl ester transfer protein (CETP), angiopoietin-related protein 3 (ANGPTL3), and apolipoprotein C-III (apoC-III) have lately been explored in clinical trials, despite the fact that about 80 genes are linked to hypercholesterolemia." (PMID 36138787, 2022).